CD4 (CD4 molecule)
Diseases named in the same sentence as CD4 in open-access papers (continued):
Sharing a sentence is not in itself a finding about the gene and the disease.
tumor (continued). "Tumor-infiltrating T cells are important effector cells in the immune system, and they can be categorized into helper T cells (CD4+ T cells), cytotoxic T cells (CD8+ T cells) and regulatory T cells (Tregs)." (PMID 37124541, 2023). "In the present report, the close relationship between SLC35A2 and immune cells (especially macrophages and CD4+T lymphocytes) was also revealed in the tumor microenvironment." (PMID 37467193, 2023). "The current analysis revealed that CALR was positively related to M1 macrophages, DCs, CD8+, and CD4+ memory T cells in tumor microenvironment; conversely, CALR was negatively correlated with M2 macrophages." (PMID 36907982, 2023). "CGNL1 correlates with several immune subsets, including resting CD4 memory T cells, follicular helper T cells, activated NK cells, and M2 macrophages, signifying its multifaceted role in shaping the tumor's immune landscape." (PMID 37980450, 2023). "In a subcutaneous mouse model of melanoma, NLRC4 is essential for the generation of cytokines in TAM as well as the development of IFN‐γ‐producing CD8+ and CD4+ T cells, both of which impede tumor progression." (PMID 37752941, 2023). "As such, the abundance of major cell types (e.g., tumor, vessel, myeloid, and CD4+ T cells) strongly correlated with the proportion of tumor-covered area per ROI." (PMID 38125025, 2023). "High NSD2 expression was positively correlated with the infiltration level of CD4+ tumor-infiltrating lymphocytes (TILs) and negatively correlated with that of CD8+ TILs." (PMID 38062230, 2023). "Anti-tumor CD4+ CTL are defined by the expression of cytolytic markers and have been detected within the lymphocyte infiltrates of different human cancers." (PMID 37965314, 2023). "By contrast, mice treated with anti-CD4 or anti-CD40L at tumor implantation generated a significantly smaller secondary response." (PMID 37072485, 2023). "The more dominant immune subsets in the tumor were: the naïve CD4 T cells, regulatory T cells, activated dendritic cells, resting mast cells, M0 macrophages, and CD49a NK cells." (PMID 38107324, 2023). "CD4+ T cells can differentiate into different subsets, including Th1, Th2, Th17, and Treg cells, that have distinct functions in tumor immunity." (PMID 37345086, 2023). "Mechanistically, mouse or human CD4+ CAR T-cell-derived IFN-γ diffused extensively to act on tumor cells at distance selectively killing tumors sensitive to cytokine-induced apoptosis, including antigen-negative variants." (PMID 37248395, 2023). "Equation models tumor-specific CD4+ T cells related adaptive immune responses (e.g., cytokine related immune responses)." (PMID 36766849, 2023). "This agrees with previous studies using human PBMC and MCC tumor-infiltrating cells that demonstrate strong CD4 T cell-mediated immune responses to the LT antigen." (PMID 37711623, 2023). "CD4+ T lymphocytes play an essential role in regulating the immune system and promoting anti-tumor responses through interactions restricted by MHC II." (PMID 38213535, 2023). "PancVAX2 treatment led to the greatest number of tumor-free mice at 90 days after vaccination (8 of 15) compared with those treated with CD4 vaccine (3 of 15), CD8 vaccine (3 of 15), or PBS (0 of 15)." (PMID 38063199, 2023). "ULCA treatment also increased MCF-7 tumor infiltration of CD4+ T cells that had a predominant CD4+, CD25High, CTLA-4High phenotype, associated with T regulatory (Treg) and activated TH2 T cells." (PMID 36989357, 2023). "Apart from HOBIT, the IL2-dependent induction of the HOBIT homolog BLIMP1 was shown to be critical for induction of granzymes in tumor-specific CD4 T cells." (PMID 37654482, 2023). "These cells sample the TME for antigens that get processed endogenously and presented to CD8+ and CD4+ T cells in the tumor draining lymph node to mount tumor-specific immune responses." (PMID 37108522, 2023).
tumor (continued). "It has been proposed that, in addition to CD4+ T cells, the anti-tumor effects of anti-CTLA4 treatment depend, to some degree, on natural killer (NK) cell-mediated anti-tumor immunity." (PMID 36068918, 2023). "Gal-1 expression in the tumour inversely correlates with CD4+ and CD8+ T cell infiltration in patient samples." (PMID 36817445, 2023). "Immune dysfunction with T-cell exhaustion has been postulated as the main cause, where CD4 + and CD8 + T-cells residing in tumor tissues express TIM-3 and PD-1 on their surface." (PMID 37567938, 2023). "In tumours, CD4+ T cells mainly activate other immune cells, such as CD8+ T cells and NK cells, to enhance the immune response." (PMID 38130720, 2023). "Nevertheless, we cannot entirely exclude, as a parallel mechanism, the direct action of tumor-specific CD4+ Th cells as cytotoxic effectors, as shown in several animal models and more recently in human tumors by single-cell sequencing." (PMID 36993983, 2023). "The immunosuppressive effect induced by Treg cells was first proposed in studies on tumor rejection by using anti‐CD25 to delete CD25+CD4+ Treg cells." (PMID 37829505, 2023). "Six populations of tumor infiltrating CD8+ T cells were identified in PDAC tumors.Three distinct clusters of NK cells were identified in PDAC tumors.Thirteen populations of CD4+ T cells were identified, but a number of these had overlapping characteristics." (PMID 37537839, 2023). "To identify the circulating T cell subsets associated with effective checkpoint therapy, we isolated CD4+ and CD8+ T cells from the peripheral blood on day 18 post MC-38 tumor challenge of treated (anti-PD-L1, anti-OX40/CpG, and PDOX) and untreated mice." (PMID 36796366, 2023). "Th2 cells have also been shown to destroy tumor cells by inducing necrosis and the therapeutic effectiveness of Th2 CD4+ CAR T cells has been demonstrated in a preclinical model of myeloma." (PMID 37529610, 2023). "But we found that the density of tumor-infiltrating CD4+ T cells were significantly decreased in the OXP/Pam3CSK4 group compared to the other groups." (PMID 37945630, 2023). "Risk scores were also positively correlated with the infiltration of CD4+ T cells and CD8+ T cells, whereas they were negatively correlated with the infiltration of anti-tumor CD4+ effector memory T cells and CD8+ effector memory T cells in the TME." (PMID 37445803, 2023). "We found that CD3 (+) and CD8 (+) T cells except CD4 (+) T cells, were notably increased in tumor tissues from lungs upon genetic silencing of A20." (PMID 37607946, 2023). "While most of the immune cells were more prevalent in the liver than in the tumor counterpart, CD4 T-cells composed of regulatory T-cells, macrophages M0, and CD49a NK-cells were significantly more expressed in the tumor." (PMID 38107324, 2023). "Among them, CD4+CD69+, CD4+ANXA1+, CD4+CTLA4+, and CD4+GZMA+ were associated with diversity-high tumors, suggesting a correlation between CD4 T cell polarization and tumor diversity." (PMID 36980203, 2023). "For example, sorafenib treatment increases intratumoral infiltrating of F4/80+ tumor-associated macrophages, CD4+CD25+FoxP3+ regulatory T cells, CCL2+/CCL17+ tumor-associated neutrophils and CD11b+Gr-1+ myeloid cells in human and murine HCC models." (PMID 36906597, 2023). "This should encourage research to deepen our understanding on MHC class II regulation in different cancers as a basis for its therapeutic manipulation and killing of tumor cells by cytotoxic CD4+ CTL." (PMID 37965314, 2023). "More specifically, CD8+, CD4+, and NK1.1+ cells predominated and were twice more abundant in edited tumors on day 21, whereas the proportion of tumor-associated macrophages was significantly reduced." (PMID 37024121, 2023). "LDH5 was directly related to high CD4+ TILs in the invading tumor front (p = 0.05, r = 0.26), while nuclear LDH5 expression was directly linked with FOXP3+ TILs (p = 0.01, r = 0.31) and FOXP3/CD8 ratio (p = 0.03, r = 0.27)." (PMID 36900270, 2023).
tumor (continued). "In contrast, recent studies have indicated that increased tumor stroma correlated with a high number of CD4+ and CD8+ TILs, leading to better patient prognosis." (PMID 37477731, 2023). "During fatty liver graft injury, arachidonic acid activated NLRP3 inflammasome in MDSCs through FATP2, which subsequently stimulated CD4+ T cells producing IL-17 to promote tumour recurrence post transplantation." (PMID 37916155, 2023). "In fact, in established cSCC, tumor-infiltrating leucocytes, specifically CD4+ and cytotoxic CD8+ T cells, had a reduced density both in intra- and peritumoral tissues in immunosuppressed patients compared to healthy patients." (PMID 37175661, 2023). "HPV-driven tumors, particularly in the oropharynx, exhibit an increased immune response characterized by higher tumor infiltration of CD4+ and CD8+ T cells, B cells, dendritic cells, and M1 macrophages, as well as a decrease in M2 macrophages and neutrophils." (PMID 38136358, 2023). "Tumor resection caused significant changes in the proportion and absolute number of CD4+CD57+T and CD4+PD-1+ T, both of which showed significant decreases." (PMID 36925914, 2023). "Activation of innate immune responses ultimately leads to the selection of tumor-antigen-specific CD8+ T-cells and the accumulation of CD4+ T-cells, macrophages, and DCs in the tumor microenvironment." (PMID 37173897, 2023). "CD4+ CD25+ FoxP3+ Treg cells are immunosuppressive cells that promote tumor cell expansion and inactivate DC cells and CD8+ Tc cell activity." (PMID 37570775, 2023). "The analysis showed that CDK1 promoted tumor cell proliferation mainly through “gain” CNVs, which also negatively regulated the infiltration of multiple immune cells, including B cells, CD4+ T cells, and dendritic cells." (PMID 36950551, 2023). "A higher number of CD4+ (p = 0.0028) and CD45+ (p = 0.0221) immune cells within the tumor microenvironment were associated with longer OS of patients." (PMID 37761986, 2023). "This study assessed tumor-stromal collagen, tertiary lymphoid structures (TLSs), and TILs, including CD4+ helper T cells, CD8+ cytotoxic T cells, and FOXP3+ regulatory T cells, as TMEs of PDAC." (PMID 37191859, 2023). "Both CD4+ T and CD8+ T cells are effective in tumor immunotherapy by causing directed immune attack against tumor cells." (PMID 38136311, 2023). "MHC class II expression is suppressed by TLR2 activation on microglia, limits CD4+ T cell-dependent antitumor immunity, diminishes the antigen presentation ability of microglia, and enhances the immunosuppressive profile of the tumor microenvironment." (PMID 37700840, 2023). "Recent evidence suggests that patients suffering from cancer exhibit an elevation in regulatory T cells population, a subset of CD4+ T cells, which suppress tumor recognition and elimination by cytotoxic T cells." (PMID 36992127, 2023). "For instance, CD86–CTLA4 interactions marked the immunoregulatory effects of CD4 Tregs within the tumour immune microenvironment, whereas MDK–LRP1 interactions promoted immune‐tolerant phenotypes in macrophages and induced CD8+ T‐cell dysfunction." (PMID 36967539, 2023). "The immunophenotype of these tumor cells is characterized by the expression of CD4, CD56, CD123, TCL-1, and CD303." (PMID 36800625, 2023). "During experiments, animal serum levels of IFN-γ were altered, which is important for tumor angiogenesis inhibition by CD4+ T cells." (PMID 36839658, 2023). "Melanoma cells express MHC II molecules and attract tumor-specific CD4+ T-cells probably via LAG-3 interaction which negatively affects the response of CD8+ T-cells." (PMID 37509517, 2023). "In conclusion, immunostimulatory cells such as DCs are one key step to activate an anti-tumor immune response; they can present tumor-associate antigen to CTL and secrete cytokines to activate CD4+ T or NKs." (PMID 36976060, 2023).
tumor (continued). "Th-17 is one of the inflammatory CD4+ cells that play an essential role in cancer pathogenesis and anti-tumor immune response." (PMID 36993955, 2023). "This enhanced eradication of metastases was associated with increased tumor infiltration by CD8+ and CD4+ T cells expressing IFN-γ." (PMID 36793731, 2023). "We also analyzed the scRNA-seq data to determine how IL21, in combination with PD-1 blockade together, affects tumor-infiltrating CD4+ T cells in the TME." (PMID 37546701, 2023). "In this study, compared to treatment with 5-FU alone, after it was combined with MCP2, the number and proportion of CD4+T cells, the thymus index and the spleen index of tumor-bearing mice were all greatly increased." (PMID 37274637, 2023). "Staining for CD4 showed a large number of positive cells in the tumours of EP1 pIL-2, EP1 pIL-12, EP1 COMB, and SKIN LPS groups." (PMID 37629081, 2023). "CD4+ T cells are perceived to exert an anti-tumor effect mainly by helping CD8+ cytotoxic T lymphocytes." (PMID 37752167, 2023). "Measuring the abundance of CXCL13+ CD8+ and CXCL13+ CD4+ T cells together in tumor samples is a powerful biomarker of response to ICB in multiple cohorts, with higher predictive accuracy than TMB." (PMID 38066642, 2023). "The immature c-Kit+ neutrophil subsets can generate ROS by participating in oxidative mitochondrial metabolism, thereby inhibiting the immune function of CD4+ T cells and promoting tumor progression." (PMID 36817451, 2023). "Flow cytometry analysis of tumor-bearing BM revealed a significant increase in CD4+ and CD8+ T-cell activation at day 7 in treated versus control as revealed by CD69 staining." (PMID 36968140, 2023). "On the other hand, the activation of OX40 can trigger additional anti-tumoral signaling promoting Bcl-xL and Bcl-2 expression, essential for long-term T-cell survival and elimination of the tumor suppressive activity of regulatory FOXP3+CD25+CD4+ T cells." (PMID 37719008, 2023). "Significant increases of tumor-infiltrating CD4+ T cells with a memory phenotype as well as NK cells were observed." (PMID 38152397, 2023). "Previous studies on tumor therapeutic models reported that administration of tumor antigen (e.g., melanoma-associated antigen recognized by T cells-1 and Wilms’ tumor 1 (WT1))-expressing aAVCs induced potent CD4+ and CD8+ T cell responses." (PMID 36830717, 2023). "Tumor-specific T cells prime from draining lymph nodes, CD4+ and CD8+ T cells are activated to exert tumor immune effect in the primary site." (PMID 37041165, 2023). "Another intriguing observation of our study is that CD4 T cells are required whereas CD8 T cells are dispensable for HT-29 tumor control." (PMID 37185301, 2023). "Interleukin (IL)-21 is a cytokine produced by activated conventional CD4+ T lymphocytes and natural killer T cells, driving anti-tumor immunity in the skin and kidney." (PMID 38001643, 2023). "Melanoma cells that express MHC class II attract tumor-specific CD4+ T cells through their interaction with LAG3, resulting in impairing CD8+ T cell responses." (PMID 37842234, 2023). "Different levels of Mpdcd1 have been linked to changes in the lymphocyte compartment, with B lymphocytes infiltrating the tumor and T lymphocytes (CD4+ and CD8+) being inversely correlated with Mpdcd1." (PMID 36769317, 2023). "Specifically, we distinguish the tumor-specific immune abilities of CD8+ and CD4+ T cells: effector CD8+ T cells directly kill susceptible and infected tumor cells while CD4+ T cells kill tumor cells indirectly through cytokines." (PMID 36766849, 2023). "There was a significant decrease in the number of Treg (CD25+Foxp3+ in CD4+) within the tumour in mice treated with Vacc DCs as compared to untreated mice." (PMID 37660049, 2023). "While CD4+ and CD8+ T cells promote an anti-tumor inflammatory response, Tregs are an immunosuppressive subset of CD4+ T-cells and are essential to maintain homeostasis and immune tolerance." (PMID 37608898, 2023).
tumor (continued). "Further investigation revealed that the TNFRSF9+subset within tumor-infiltrating CD4+Treg exhibited potent immunosuppressive abilities." (PMID 38250084, 2023). "This activation translates into increased numbers of CD8+ and CD4+ lymphocytes infiltrating the tumor, more robust antitumor cellular responses targeting tumor antigens, and into improved antitumor activity." (PMID 37016144, 2023). "It has been reported that increased CD4 and CD8 T cell abundance in tumor immune microenvironment is associated with better survival outcomes 39,40." (PMID 37283800, 2023). "In-depth immunological studies revealed that generally tumor cells decrease the CD4+/CD8+ ratio and inhibit T-cell functions to escape from immune surveillance." (PMID 38139779, 2023). "With the help of functional intravital imaging, we report that interferon (IFN)-γ production but not perforin-mediated cytotoxicity was the dominant mechanism for tumor elimination by anti-CD19 CD4+ CAR T cells." (PMID 37248395, 2023). "Immune escape phenomena are well known in the tumor microenvironment in which regulatory T-cells (Treg) and tumor-associated macrophages (TAM) suppress CD4+ and CD8+ T-cell activation." (PMID 37373202, 2023). "CD4+ T cells have recently been highlighted as playing important roles in regulating the anti-tumor immune response." (PMID 37033978, 2023). "A substantial fraction of T cell-recognized cancer neoantigens is restricted by MHC class II molecules, and CD4+ T cells recognizing such MHC class II-restricted neoantigens contribute to tumor control." (PMID 36593398, 2023). "PD-1 was expressed highly within the tumor microenvironment and present on 64% and 71% of CD4+ and CD8+ T cells respectively within TIL." (PMID 36689623, 2023). "By secreting a variety of cytokines and helping CD8 + cytotoxic T cells in dissolving and eliminating tumor cells, CD4 T cells predominantly mediate anti-tumor immunity." (PMID 37189020, 2023). "PD-1 can be also expressed in TILs and, on the other hand, tumor cells can express PD‐L1 in different percentage, contributing to the inhibition of CD4+ and CD8+ T-cell activation and to the apoptosis of antigen-specific T-cell clones." (PMID 36776840, 2023). "Contrastingly, Th2-polarized CD4+ T cells are imperative pro-tumorigenic components for tumor cell survival and proliferation." (PMID 37637063, 2023). "They compared the phenotype and tissue distribution of CD8+ T cell and CD4+ T cell among blood, normal tissue, tumor tissue." (PMID 37063862, 2023). "Consistently, silencing CD39 and/or CD73 increased anti-tumor activity of human CD4+ T cells against ovarian cancer cells." (PMID 37287049, 2023). "For this purpose, we performed in a collective of OSCC a clinical data collection as well as immunohistochemical staining of some of the most important tumor-infiltrating immune cells, i.e., CD4+, CD8+, and FoxP3+ T-cells as well as CD1a+ DCs." (PMID 37345025, 2023). "The results demonstrated that after 24 hours, 35% of the tumor spheroid was dead in the presence of ML-NK cells alone, whereas in the co-culture with CD4+ T cells 50% of the area was dead." (PMID 37865647, 2023). "According to the univariate logistic regression analysis, we identified 6 prognostic factors, including PSA, Gleason score, tumor stage, nodal metastasis, CD4+ TIL density and NSD2 expression (P < 0.05)." (PMID 38062230, 2023). "Foxp3+CD25+CD4+ regulatory T (Treg) cells can suppress the function of cytotoxic T lymphocytes (CTLs), which are crucial for tumor cell recognition and killing." (PMID 37908722, 2023). "On that account, we focused on investigating such relevance, finding that C1QC expression in KIRC presented a positive association with tumor-infiltrating immune cells like B cell, CD8+ T cell, CD4+ T cell, macrophage, neutrophil, and dendritic cell." (PMID 36992705, 2023).